POSTN (periostin)
Diseases named in the same sentence as POSTN in open-access papers (continued):
Sharing a sentence is not in itself a finding about the gene and the disease.
cancer (continued). "A significant positive correlation was found between the expression of POSTN (in cancer cells/CAFs) and the expression of the analyzed pro-angiogenic factors (CD31, CD34, CD105, and VEGF-A) and MVD in the entire population of patients with NSCLC and individual histological subtypes (AC, SCC)." (PMID 39272978, 2024). "In conclusion, a high expression of POSTN (in cancer cells and CAFs) may be crucial for angiogenesis and NSCLC progression and can constitute an independent prognostic factor for NSCLC." (PMID 39272978, 2024). "Two cancer-associated fibroblast marker genes, CTHRC1 and POSTN, were clustered here." (PMID 39850884, 2024). "In conclusion, POSTN‐positive cancer cells activate both CAFs and macrophages." (PMID 38389400, 2024). "Moreover, periostin (PN) is a secreted extracellular matrix protein that is commonly expressed in CAFs in several cancers." (PMID 38649701, 2024). "By interacting with the growth factor VEGF-A and binding to EC integrins (αvβ3, αvβ5, and α6β4) and cancer cells, POSTN activates intracellular signaling pathways (PI3K, AKT/PKB, FAK, and Erk/VEGF), which leads to increased cell survival, angiogenesis, invasion, and metastasis." (PMID 39272978, 2024). "Moreover, POSTN enhances the invasiveness of both primary cancer cells and transformed epithelial cell lines." (PMID 39329988, 2024). "Furthermore, to suppress cancer POSTN with exon 17, 4T1 cells transfected with POSTN exon 17 skipping oligo or control oligo were transplanted from the tail vein into the lungs." (PMID 39272982, 2024). "Periostin, firstly recognized as a protein specifically expressed in periosteal tissues, is expressed in a wide variety of normal adult and fetal tissues, under stress conditions and in cancer." (PMID 38969910, 2024). "POSTN is expressed at extremely low levels in healthy tissues but is overexpressed in cancers." (PMID 39227950, 2024). "The expression of POSTN in cancer cells increases in response to hypoxia." (PMID 39329988, 2024). "Additionally, significant differences were found in the expression of POSTN in cancer cells between G2 and G3 tumors in the entire NSCLC group and in the AC and SCC subtypes (*** p < 0.001)." (PMID 39272978, 2024). "Pathological POSTN was secreted from CAFs in stroma surrounding cancer cells and cancer cells themselves, but it is unclear whether the stroma or cancer pathological POSTN should be suppressed." (PMID 39272982, 2024). "Indeed, using RNAseq analysis, we were able to see higher expression of FASN in cancer cells cultured in conditioned medium containing exogenous periostin." (PMID 38049490, 2023). "We also suggest that POSTN Iso5 can be a useful marker for detecting cancer cells undergoing EMT." (PMID 36691359, 2023). "In previous studies, POSTN expression was observed in both cancer cells and stromal cells." (PMID 36691359, 2023). "Additionally, FASN induced in cancer cells by elevated exogenous periostin plays important roles in lipid metabolism to generate excessive amounts of free fatty acids, which are then broken down into acetyl-CoA52." (PMID 38049490, 2023). "We speculate that, although CTHRC1 is an important multi-functional regulatory molecule in the TME, its regulatory effects on cancer cell migration/invasion are largely dependent on the POSTN expression of PSCs." (PMID 37444482, 2023). "We suggest that POSTN Iso5 can be a useful marker for detecting cancer cells undergoing EMT." (PMID 36691359, 2023). "Inhibition of POSTN may be a promising therapeutic strategy against solid malignancies via repression of both cancer and stromal cells." (PMID 36765564, 2023). "High serum periostin levels have been observed in several types of cancers." (PMID 36598904, 2023). "Interestingly, POSTN expression is frequently observed in cancer cells with higher p‐EMT score by using a previous single‐cell transcriptomic data of HNSCC cases." (PMID 36691359, 2023).
cancer (continued). "Among these, periostin, encoded by the gene POSTN, is a key player in tissue repair and remodeling and plays a role in several immune-mediated inflammatory conditions and in cancer development and progression." (PMID 38049490, 2023). "Due to the role of FASN in de novo fatty acid synthesis, our data suggest that lipid metabolism in cancer cells could be altered through increased FASN expression in response to an environment with higher periostin levels." (PMID 38049490, 2023). "POSTN interacts with cell-surface receptor integrins such as αvβ3, αvβ5, and α6β4 to modulate intracellular signaling pathways in cancer cells and accelerate cell adhesion, survival, invasion, angiogenesis, metastasis, and epithelial–mesenchymal transition (EMT)." (PMID 36765564, 2023). "It has been widely accepted that POSTN is closely involved in cancer progression." (PMID 36691359, 2023). "The deregulation of POSTN occurs in cancers, cardiovascular diseases, and respiratory disorders." (PMID 37919719, 2023). "Periostin (coded by the POSTN gene) has a central role in the CTHRC1–PSCs–cancer metastasis axis." (PMID 37444482, 2023). "Moreover, POSTN is frequently overexpressed in some cancers, and its various isoforms are generally believed to exhibit tissue-specific expression." (PMID 38020106, 2023). "We suggest that periostin may serve as a potential target to increase cancer cell-NK interaction resulting in the stimulation of cell death." (PMID 36830807, 2023). "Together, these results suggest that POSTN facilitates attraction of monocytes and differentiation into TAMs by directly or inducing the expression of NF-κB-dependent cytokines and chemokines from cancer cells." (PMID 36550569, 2022). "In the recent years, periostin (POSTN), a gene encoding an extracellular matrix protein with similarity to fasciclin family has emerged as a potential biomarker for various types of cancers." (PMID 36544136, 2022). "The expression of POSTN in pan-cancer and NSCLC tissues are significantly increased." (PMID 35281822, 2022). "Our study has indicated that the expression of POSTN in cancer cells may be an independent prognostic factor for survival in patients with NSCLC and the particular histological subtypes, i.e., AC and SCC." (PMID 35163164, 2022). "Some reports have indicated that periostin plays an important role in numerous cancers." (PMID 35056404, 2022). "Furthermore, we noticed, for the first time, a strong positive significant correlation of POSTN in cancer epithelial cells with stromal POSTN expression (CAFs) in the whole cohort of patients as well as in the particular histological types (i.e., AC and SCC)." (PMID 35163164, 2022). "In head and neck squamous cell carcinoma, POSTN secreted by CAFs might promote cancer stemness through interacting with protein tyrosine kinase 7-Wnt/β-catenin signalling pathway in cancer cells." (PMID 35260891, 2022). "Given the well-known role of periostin in cancer development, Periostin targeted therapy could be an effective treatment approach." (PMID 36224629, 2022). "This indicates the influence of POSTN in cancer development." (PMID 35163164, 2022). "Finally, it has been reported that activating protein tyrosine kinase 7 periostin promotes cancer stemness." (PMID 35056404, 2022). "On the basis of these findings, it seems that periostin derived from different cancer cell types may bind to various integrin receptors." (PMID 36224629, 2022). "Periostin also plays an important role in fibrosis and cancer." (PMID 36359752, 2022). "Additionally, in non-small-cell lung cancer, it has been observed that increased periostin expression is a response of cancer cells to hypoxic conditions." (PMID 35056404, 2022). "The role of periostin in cancer will be discuss in following sections." (PMID 36224629, 2022). "In addition, bioinformatics analysis revealed that the p73/periostin axis is predictive of a poor prognosis in various cancer types." (PMID 36224629, 2022).
cancer (continued). "Furthermore, they noticed that FAK knockdown attenuated MMP levels, cell migration, and invasion, which were all enhanced by POSTN, suggesting that POSTN plays a critical role in the multistep cascade process of cancer metastasis." (PMID 35163164, 2022). "Silencing of the periostin gene (POSTN) can inhibit the biological process of several different cancers, and this inhibition may be related to down-regulation of PI3K/AKT signaling." (PMID 35057799, 2022). "Additionally, periostin can promote EMT in several types of cancer cells, contributing to the promotion of metastasis and invasion of cancer." (PMID 35056404, 2022). "In addition, the expression and function of POSTN in stromal cells and the communication between POSTN and cancer cells are yet to be elucidated." (PMID 35832544, 2022). "Once these POSTN‐positive CAFs get ‘older’, they may lose POSTN expression, as suggested by our in vitro cancer‐educated experiment." (PMID 36102377, 2022). "As a protein with multiple functional domains, POSTN can interact with different proteins and may be involved in cancer progression." (PMID 36077762, 2022). "However, several questions related to the function of various isoforms of periostin, especially in cancer, tissue distribution of isoforms, overexpression in cancer tissues, and interaction with different molecules such as integrins, remain unanswered." (PMID 36224629, 2022). "Recent studies have also shown that POSTN plays an important role in cancer treatment resistance." (PMID 36172351, 2022). "Periostin is overexpressed in a variety of solid epithelial tumors, and its interaction with cell-surface receptor integrins, which modulates intracellular signaling pathways, has a direct effect on cancer hallmarks." (PMID 36224629, 2022). "POSTN expression in cancer cells may be considered to be an independent prognostic factor for survival in NSCLC." (PMID 35163164, 2022). "Similarly, an IKKβ inhibitor, TCPA-1, reduced cytokine expression in the POSTN-overexpressing cancer cells." (PMID 36550569, 2022). "POSTN has been shown to promote angiogenesis in malignant tumors." (PMID 35832544, 2022). "According to previous studies, periostin may serve as a chemoattractant for cancer cells and is important for metastatic cell colonization by conditioning the premetastatic niche." (PMID 36224629, 2022). "POSTN enhanced integrin/ERK/NF-κB signaling through an autocrine effect on cancer cells to produce macrophage attracting and mobilizing cytokines including MIP-1β, MCP-1, TNFα and RANTES resulting in increased chemotaxis of THP-1 monocytes and their polarization to M2 macrophages in vitro." (PMID 36550569, 2022). "Furthermore, we noticed a significant correlation of POSTN expression in cancer cells with MMP-2 expression levels in NSCLC." (PMID 35163164, 2022). "Periostin is a non-structural extracellular matrix protein secreted from the remodeled heart and associated with cancer progression and metastasis." (PMID 34696798, 2021). "The effect of periostin on cancer progression needs to be confirmed in vivo." (PMID 34696798, 2021). "POSTN was previously identified in stromal cells surrounding a variety of malignant tumors." (PMID 33919736, 2021). "In addition, overexpressed POSTN was thought to be related to various cancers, including colon cancer, lung cancer, pancreatic cancer, and prostate cancer 12-15." (PMID 34093819, 2021). "Periostin-targeted therapy for cancer has recently been developed." (PMID 34702952, 2021). "Moreover, we found pulmonary metastases in the mice implanted with cancer cells with high POSTN expression, even though there were only two mice, and no metastasis was found in the mice implanted with cancer cells with low POSTN expression." (PMID 34193219, 2021). "Periostin expression in lung fibroblasts may be modulated by cancer cells through the secretion of transforming Growth Factor Beta 3 (TGFβ3)." (PMID 34201840, 2021).
cancer (continued). "Periostin is a secreted protein, important in tissue development and regeneration, including wound healing; however, through binding to integrins, periostin supports adhesion and migration of epithelial cells playing a role in cancer stem cell (CSC) maintenance and metastasis." (PMID 33916703, 2021). "Based on our results, previous CAF‐targeting strategies for cancer treatment may have preferentially eliminated periostin+CAFs while leaving other CAF populations intact." (PMID 33124726, 2021). "Moreover, cancer cells are able to educate fibroblasts to produce periostin and Tenascin C (TNC), enhancing metastatic colonization of the lung." (PMID 34201840, 2021). "This hypothesis is consistent with the established role of POSTN in maintaining cancer stem cells and warrants further investigation in the future." (PMID 34490258, 2021). "Previous study suggested POSTN was involved in RCC migration and invasion 18, 24, but the mechanism of between POSTN and cancer metastasis still remain unclear." (PMID 34093819, 2021). "We hypothesized that the localization of a POSTN fragment could vary in cancer–stroma interactions if there was a POSTN fragment protein with exon 17 in the POSTN C-terminus region, but not if there was exon 12 in the POSTN N-terminus region." (PMID 33919736, 2021). "Periostin (Pn) is involved in multiple processes of cancer progression." (PMID 34680221, 2021). "The overexpression of periostin and TNC is induced by skin damage, promoting the activation of fibroblasts to repair the wound, and their pathogenicity has been associated with chronic inflammation, fibrosis and cancer." (PMID 32947957, 2020). "Periostin is a secreted protein that stimulates metastatic growth by promoting cancer cell survival, invasion, and angiogenesis; thus, it can be a useful marker to predict the behaviour of cancer." (PMID 33123565, 2020). "Additionally, periostin has the ability to recruit Wnt ligands; thus, it can increase the presentation of Wnt ligands to cancer cells." (PMID 32300189, 2020). "Furthermore, periostin is an extracellular protein and accessible via the bloodstream, as such, it has been considered to be a promising therapeutic target for cancer patients." (PMID 32719746, 2020). "POSTN is also known to play a role in the resistance of cancer cells to hypoxia-induced apoptosis." (PMID 33488671, 2020). "Secondly, POSTN may have different functions according to different histopathological types of cancer." (PMID 32987711, 2020). "Thus, periostin is abundant in micrometastatic lesions undergoing neoangiogenesis and is a profound factor for a permissive microenvironment of cancer metastasis." (PMID 32300189, 2020). "Periostin expression was detected in the cytoplasm of cancer cells in all cases." (PMID 33123565, 2020). "The periostin levels elevated in all cancer groups compared to the benign lung lesion group." (PMID 32719746, 2020). "Once cancer cells have disseminated, the de novo activation of fibroblasts at secondary sites favours the establishment of macrometastases via multiple mechanisms, including the production of matrix components such as tenascin and periostin that provide supporting signals to the cancer cells." (PMID 31980749, 2020). "Comparison between patients categorized according to biomarker expression, using formula A, i.e. [KLK6/CEACAM5 + SLC35D3/CEACAM5 + POSTN/18S rRNA -MUC2/CEACAM5], with regard to risk for recurrence of disease and cancer death and observed recurrence 3 and 5 years after curative surgery." (PMID 32049988, 2020). "At the same time, some researchers have suggested that POSTN can be detected in cancer cells." (PMID 32987711, 2020). "Periostin is also known to play a significant role in tumorigenesis via the promotion of EMT of carcinoma cells and the regulation of the integrin signaling pathways, which leads to subsequent activation of the AKT/PKB (protein kinase B) and the FAK (focal adhesion kinase) network." (PMID 32719746, 2020).
cancer (continued). "In cancer studies TW dimerization has not been linked to regulation of POSTN expression, however, in mouse cranial suture development, TW homodimers upregulate POSTN in the osteogenic front." (PMID 31540485, 2019). "Periostin is an extracellular matrix protein found in a number of tissues, including the PDL, periosteum, cardiac valves, alveolar wall, and cancer-associated stroma, and has multiple functions including involvement in extracellular matrix assembly and in cell adhesion." (PMID 31031642, 2019). "Little is known regarding mechanisms by which TW regulates POSTN yet their elucidation could be critical for devising therapeutic strategies to disrupt their functional effects in cancer." (PMID 31540485, 2019). "Periostin induces many other cancer promoting abilities when administered to various cell lines." (PMID 31572679, 2019). "Furthermore, exosomes are involved in cell-cell communication processes, and previous studies have demonstrated that metastatic cell-secreted exosomes were rich in POSTN content, and regulated cancer metastasis." (PMID 31167519, 2019). "In fact, increased POSTN levels have been detected in serum of patients with some malignant tumors suggesting that it could be an effective biomarker, both for diagnosis and survival prediction." (PMID 29946533, 2018). "Periostin is known to be expressed by fibroblasts in RA, carcinomas and other malignant tumours." (PMID 30202513, 2018). "Next, we will review the current knowledge about deregulation of POSTN expression in cancer." (PMID 29946533, 2018). "However, in other study, patients with high POSTN expression in both, stroma and cancer epithelial cells had the shortest overall survival and progression-free survival." (PMID 29946533, 2018). "Extracellular vesicles isolated from urine of patients had markedly higher levels of POSTN than controls, indicating that POSTN could be a potential urinary biomarker of cancer progression." (PMID 29946533, 2018). "In addition to its ability to predict outcome, and perhaps for this, POSTN has been shown to induce resistance to some chemotherapeutic drugs in determined cancer cell types." (PMID 29946533, 2018). "Several studies carried out in preclinical models suggest that blocking POSTN could be an attractive strategy to treat cancer." (PMID 29946533, 2018). "In this review, we will focus on the role of POSTN in the development and progression of cancer." (PMID 29946533, 2018). "The accumulated knowledge about the relationship between POSTN and cancer in the last two decades indicate that this matricellular protein play an important role in cancer development and progression, beyond its implications in the homeostasis of specialized tissues." (PMID 29946533, 2018). "Furthermore, the relationship between POSTN and the proteins involved in the multidrug resistant phenotype in cancer (i.e., ABC family of transporters) should be also studied in more detail." (PMID 29946533, 2018). "This association between POSTN and resistance to anticancer drugs suggests that could be necessary design new combinational therapies in determined types of cancer to precisely circumvent the effect of the POSTN." (PMID 29946533, 2018). "Curiously, POSTN has been also shown to inhibit EMT in others cancer cells." (PMID 29946533, 2018). "Antibody targeting cancer-specific variants of periostin also halted disease progression after chemotherapy without toxicity in mice, suggesting its potential as a therapeutic agent to combat chemoresistance." (PMID 29507310, 2018). "Furthermore, POSTN mRNA expression is significantly correlated with an EMT gene signature in Cancer Cell Line Encyclopedia (CCLE) database." (PMID 29507310, 2018). "In addition, there are strong experimental evidences that involve POSTN in the acquisition of many hallmarks of cancer, such as proliferation, invasion and metastasis, angiogenesis, or cell survival." (PMID 29946533, 2018).